AHR (aryl hydrocarbon receptor)
Diseases named in the same sentence as AHR in open-access papers (continued):
Sharing a sentence is not in itself a finding about the gene and the disease.
glioblastoma (continued). "The production of Kyn and its metabolites by TDO was shown to reach concentrations sufficient to activate the AHR pathway in the tumor microenvironment (TME) of a glioblastoma model." (PMID 32782249, 2020). "In glioblastoma-infiltrating tumor-associated macrophages, STAT3 acts as a positive regulator of aryl hydrocarbon receptor (AHR) and thus increases the recruitment of tumor-associated macrophages and tumor growth." (PMID 32972405, 2020). "A recent paper using a glioblastoma model showed an AHR-driven upregulation of the ectonucleotidase CD39 in TAMs which promoted T cell dysfunction." (PMID 32782249, 2020). "Kynurenine produced by glioblastoma cells activates aryl hydrocarbon receptor (AHR) in TAMs to modulate their function and T cell immunity." (PMID 33374253, 2020). "In glioblastoma, activation of the aryl hydrocarbon receptor (AHR) by dysregulation of the kynurenine pathway contributes to the malignant properties of these tumors." (PMID 32326073, 2020). "A recent study showed that the AhR exhibited tumor suppressor-like activity in established and patient-derived glioblastoma cells and genomic analysis showed that this was due, in part, to suppression of CXCL12, CXCR4 and MMP9." (PMID 32731514, 2020). "It was observed that, in a mouse model of glioblastoma, TAMs express aryl hydrocarbon receptor (AHR), which, upon activation by tumor released kynurenine (KYN), upregulates CCR2 expression." (PMID 31547627, 2019). "More recently, a tryptic AhR-transforming growth factor-ß (TGF-ß)-integrin has been a suspected to play a significant role in glioblastoma malignancy, as the AhR upregulates the expression of several members of the TGF-ß pathway in malignant glioma cells." (PMID 30149528, 2018). "In support of the AHR driving tumor aggression, AHR knockdown in lung adenocarcinoma or oral squamous cell carcinoma, or depletion of putative endogenous AHR ligands in glioblastoma decreases anchorage-independent growth and/or invasion." (PMID 29735912, 2018). "ITE, an agonist of the aryl hydrocarbon receptor, also significantly attenuated the Akt-mediated phosphorylation of Oct4 in glioblastoma and liver cancer cells, and reduced their tumorigenic potential in a xenograft tumor model." (PMID 25625591, 2015). "Moreover, Kynurenine, produced by glioblastomas, activates the aryl hydrocarbon receptor (AHR) in macrophages, resulting in the induction of CD39 expression and enhanced adenosine production, which suppresses CD8+ T cell immunity and promotes GBM progression." (PMID 40076738, 2025). "Interestingly, recent studies on glioblastoma cells show that AhR enhances autophagy under the influence of reduced tryptophan levels." (PMID 40810764, 2025). "Researchers concluded that rutaecarpine may be considered a potent AhR activator, leading to the suppression of glioblastoma cell migration." (PMID 40286187, 2025). "Furthermore, AhR was found to be a direct repressor of the expression of Oct-4 in glioblastoma cancer stem cells, where treatment with the tryptophan derivative ITE promoted the differentiation of GBM CSC and suppressed the growth of GBM xenografts." (PMID 37106727, 2023). "In conclusion, we found that rutaecarpine is a natural compound with AhR activation activity, which can inhibit the migration of U87 human glioblastoma cells by activating the AhR signaling pathway and inducing the expression of downstream tumor suppressor IL24." (PMID 34955744, 2021). "However, the endogenous ligand(s) responsible for the basal activation of AhR remains a mystery in glioblastoma cells." (PMID 34955744, 2021). "Thus, a better understanding of Trp metabolism in glioblastoma is required to address therapy resistance and to select the patients that will benefit from treatments targeting TCEs and AHR." (PMID 34646367, 2021). "Therefore, we aim to explore the effects of rutaecarpine on the migration of human glioblastoma cells U87 and the involvement of the AhR signaling pathway." (PMID 34955744, 2021).
glioblastoma (continued). "Finally, analysis of the effect of AHR activation on overall survival using the GBM TCGA data revealed that glioblastoma patients showing high AHR activity are at a twofold higher risk of worse overall survival." (PMID 34646367, 2021). "Moreover, a recent study revealed that glioblastoma cell-derived kynurenine activates AHR (aryl hydrocarbon receptor) in TAMs to modulate TAM recruitment and T cell dysfunction." (PMID 33391518, 2021). "In addition, kynurenine produced by glioblastoma cells can activate the aromatic hydrocarbon receptor (AHR) in TAMs, and AHR can drive KLF4 expression and inhibit NF-κB activation in TAMs, which regulate TAM function and T cell immunity." (PMID 33365025, 2020). "To determine whether the regulation of KYN pathway genes by AHR might also occur in CNS-derived cells, we used an astrocyte-derived cell line, the U-87 MG glioblastoma cells, to perform experiments parallel to those performed with HepaRG cells." (PMID 29317604, 2018). "Additionally, recent studies have indicated that AHR is involved in the TGF- β1/SMAD pathway in glioblastoma pathogenesis." (PMID 20664703, 2010). "Moreover, glioblastoma cells can produce kynurenine that activates AHR in TAMs; AHR recruits TAMs through CCR2/CCL2, drives the expression of the ectonucleotidase CD39 in TAMs, and plays a synergistic role with CD73 to promote adenosine production, leading to CD8+ T-cell dysfunction." (PMID 36466873, 2022). "However, the AhR expression is variable in different glioblastoma cells." (PMID 34955744, 2021). "As mesenchymal glioblastoma is characterized by high infiltration with immune cells, we went on to analyze publicly available single cell RNA-seq data of glioblastoma 7 for Trp metabolism and AHR activity in order to identify the cell types contributing to these processes." (PMID 34646367, 2021). "AhR plays an important role in clonogenic survival, motility, promoting pro-oncogenic cytokine production such as TGF-β, immunosuppression by its effects on T-cells, DCs, macrophages, natural killer cells, B-cells, or glioblastoma-specific tumor-associated macrophages." (PMID 34819875, 2021). "However, our results identify the AhR as a viable drug target for treating glioblastoma and this could include specific SAhRMs and also other AhR-active benzimidazole that might mimic the effects of omeprazole." (PMID 32731514, 2020). "For example, the AHR is hyper-expressed and “constitutively” active (likely a reflection of the presence of endogenous AHR ligands) in a diverse array of human cancers including glioblastomas, adult T cell leukemias, and oral cavity, lung, liver, prostate and Her2+ breast adenocarcinomas." (PMID 29735912, 2018). "Immunohistochemical analysis on glioblastoma TMA cores showed variable cytoplasmic expression of IDO1, IDO2, and TDO2, while AhR showed variable nuclear expression in tumour cells across GBM patients." (PMID 38951170, 2024). "Our work shows that glioblastoma patients with high expression of IDO1/2, TDO2 and AhR at diagnosis have a poorer prognosis compared to patients with low expression levels." (PMID 38951170, 2024). "further suggests that IL4i1 activates the expression of AHR, IDO, and TDO2, which collectively suppress tumor immunity in the hypoxic TME of glioblastoma derived GBM cells, thereby promoting cancer progression." (PMID 38605962, 2024). "It was confirmed in glioblastoma that the IDO-catalyzed tryptophan metabolite kynurenine curbed the infiltration of Teffs by binding to and stimulating aryl hydrocarbon receptor (AHR), an essential cytoplasmic transcription factor." (PMID 35948909, 2022). "C/EBPβ as well as COX-2 have recently been found to maintain the constitutive expression of Kyn-producing TDO in human glioblastoma, suggesting that this transcription factor and COX-2 critically shape the pro-tumorigenic properties of AhR." (PMID 33763068, 2021).
glioblastoma (continued). "Tryptophan (Trp)-catabolic enzymes (TCEs) produce metabolites that activate the aryl hydrocarbon receptor (AHR) and promote tumor progression and immunosuppression in glioblastoma." (PMID 34646367, 2021). "Meanwhile, we propose AhR and IL24 as composite targets for screening anti-glioblastoma migration compounds." (PMID 34955744, 2021). "They showed integrin inhibition to be a prospective strategy to tumor inhibit angiogenesis and to restrain the AhR- and TGF-β-controlled characteristics of malignancy in glioblastomas." (PMID 29487603, 2018). "Further, the correlation analysis of AhR and FTO expression in 169 glioblastoma samples revealed that AhR expression was negatively correlated with FTO expression (R = −0.238, p = 0.008), indicating that IDO1 inhibits FTO activity by promoting AhR expression and nuclear translocation." (PMID 39863603, 2025). "In line with this, AhR activation promoted expression of immunosuppressive programmed death-ligand 1 (PDL1) in TAMs, and AhR inhibition mildly decreased the tumor size and improved the CD8 to Treg ratio in a separate glioblastoma model." (PMID 38339226, 2024). "The kynurenine pathway is hyperactive in glioblastoma and it supports tumor development and progression, although perhaps not by engaging the aryl hydrocarbon receptor, AHR." (PMID 35806160, 2022). "A recent study suggests that AhR performs a tumor suppressor-like rather than promoter function in glioblastoma and its suppression facilitates invasion of cancer cells." (PMID 34769098, 2021). "The expression of select AHR target genes, including AHR itself, positively correlated with TDO2 expression and to a lesser extent with IDO1 expression, pointing towards TCE-mediated AHR activation in glioblastoma." (PMID 34646367, 2021). "Moreover, our lab recently discovered that the transcription factor aryl hydrocarbon receptor (AHR), which is necessary for glioblastoma growth, mediates the expression of DHODH and UMPS in MYC-overexpressing fibroblasts and glioblastoma cells." (PMID 33201894, 2020). "Indeed, AHR expression was clearly detected in glioblastoma regions in a biopsy, while its expression was low in non-tumor regions." (PMID 40711040, 2025). "On the other hand, conflicting reports have demonstrated that kynurenine does not alter AhR activity or invasion of glioblastoma cells, and that the AhR antagonist, CH-223191, inhibits glioblastoma invasion in an AhR-independent manner in both AhR-expressing and AhR-silent cell lines." (PMID 38807762, 2024). "Additionally, non-glucosylated emodin inhibits U87 glioblastoma cell migration by activating the aryl hydrocarbon receptor (AhR) signaling pathway." (PMID 37959784, 2023). "Next, they treated glioblastoma (GBM) cells with IL4I1-derived metabolites, which increased the nuclear localization of AHR and enhanced AHR target genes transcription." (PMID 33692337, 2021). "The effects of omeprazole on glioblastoma cell invasion are AhR-dependent but that does not preclude contributions of other pathways Several review articles summarize the anticancer activities and safety concerns of omeprazole and related proton pump inhibitors and their effects are variable." (PMID 32731514, 2020). "Therefore, the AhR-dependent mechanism reported in this study may not exist in glioblastoma cells that express very little or no AhR." (PMID 34955744, 2021).
colon carcinoma (63 papers, 2009 to 2025). "Different laboratories have investigated the impact of deficiencies in AhR in intestinal cancers using colon cancer models that are driven by colonic inflammation and tumor promotion downstream of chemical insults, pathogen infections, or high-fat diets." (PMID 37106727, 2023). "We also observed that in APCS580/+; KrasGD12/+ mutant mice that loss of AhR activates colon stem cells and colon cancer and Wnt signaling." (PMID 38651159, 2023). "We then evaluated potential impact of the AhR deficiency on proliferative behavior of colon carcinoma HT-29 and HCT116 cells lines." (PMID 36077780, 2022). "This enzyme has been poorly studied in cancer, however, a recent report indicated that the proto-oncogen MYC induces AFMID expression in colon cancer, and it is associated with cell proliferation through an AhR modulation by KYN." (PMID 36355137, 2022). "Treatment of colon cancer cells with sulindac sulfide in vitro causes upregulation of inflammation and cancer-promoting genes through AHR." (PMID 26183215, 2015). "The anticarcinogenic effects of AhR have also been highlighted in the APCMin/+ colon cancer mouse model, driven by the loss of the tumor-suppressive function of adematous polyposis coli (APC), resulting in excess stem cell proliferation downstream from the increased β-catenin levels." (PMID 37106727, 2023). "Our results show that the loss of AhR or its chemical inhibition may lead to the disruption of growth and metabolism of colon cancer cells, when cultured under standard in vitro conditions." (PMID 36077780, 2022). "This indicated that whereas SCD1 could be controlled directly by the AhR activity, the effects on other FA synthesis and regulatory genes could be linked to the impact of AhR on cell proliferation and metabolism in colon cancer cells." (PMID 36077780, 2022). "However, AhR deficient mice had a more rapid progress of colon carcinoma compared to wild-type mice." (PMID 33278884, 2020). "Interestingly, AhR-deficient mice frequently develop colon tumor with abnormal accumulation of β-catenin protein." (PMID 25360135, 2014). "Thus, in addition to decreased cell proliferation and ATP production, AhR deficiency may also lead to deregulation of FA synthesis in colon cancer cells." (PMID 36077780, 2022). "In a mouse colon cancer model, TDO expression significantly enhanced liver metastasis, primarily by inducing AHR-mediated PD-L1 transactivation, which suppressed the immune response and promoted liver metastasis of colon cancer." (PMID 39940736, 2025). "Our findings suggest that restoring the host–microbe balance at the intestinal mucosa via targeting AhR is an effective therapeutic approach to inhibit IBD and potentially IBD-associated colon cancer." (PMID 39894796, 2025). "In brief, THP-1 (human monocytes) and Caco-2 cells (human colon cancer epithelial cells) were exposed to the different molecules herein synthesized, or to a well-described AHR agonist, FICZ, as control." (PMID 38998940, 2024). "At the same time, various other publications suggest a tumor promoting role for AhR in colon cancer." (PMID 38807762, 2024). "In spheroids developed from human colon cancer samples, stemness characteristics were dependent upon AhR expression." (PMID 38339226, 2024). "The activation of the tryptophan 2,3-dioxygenase-2 (TDO2)–Kyn–AhR pathway promoted liver metastases of colon cancer in a mouse model by aiding in immune evasion and maintaining stemness." (PMID 38434684, 2024). "This further improves the uptake of tryptophan and its alteration in colon cancer cells to kynurenine (Kyn), leading to the nuclear translocation of AHR in these cells." (PMID 39201782, 2024). "TDO2 promotes metastasis of colon cancer cells to the liver, upregulates programmed death ligand 1 (PD-L1) and suppresses immune responses, and maintains Wnt signaling in an AhR-dependent manner." (PMID 38807762, 2024).
colon carcinoma (continued). "Due to this, it is necessary to further research amongst both the agonists and antagonists of AhR to improve our understanding of their effects in colon cancer, given the potential of AhR as a target of interest in cancer treatment and prevention." (PMID 38518996, 2024). "In colon tumor cells, inhibition of AhR activity decreases the expression levels of SCD-1, a key enzyme of the biosynthetic pathway, and SREBP, a transcriptional regulator of adipogenesis, to restrict cancer cell proliferation in a cell-specific manner." (PMID 38434684, 2024). "The universal oncogene MYC transcription in colon cancer cells first induces the particular profile of AHR in that cancer; AHR then promotes MYC-induced proliferation by turning on the expression of the genes needed for biomass generation." (PMID 39201782, 2024). "As another example, 3-methylcholanthrene (3MC) upregulates ABCG2 expression in colon cancer LS174T cells via the activation of AHR which binds to the AHR response element 5 within ABCG2 promoter region and thus activate the transcription of ABCG2." (PMID 39114355, 2024). "In human poorly differentiated colon carcinoma cell line RKO in vitro, TCDD-activated AhR causes an increase in the β-catenin levels." (PMID 37232717, 2023). "There is an example of a different influence on AhR signaling in HCT116 human colon carcinoma cells, where the suppression of β-catenin potentiated the induction of the expression/activity of CYP1 enzymes by BaP." (PMID 37232717, 2023). "In contrast, some studies reported alternative results showing that the AhR exhibited pro-oncogenic activity primarily in colon cancer cell models." (PMID 38651159, 2023). "The AhR regulates anti-inflammatory activities in the gut and both the receptor, and its ligands protect against intestinal inflammation and development of colon cancer." (PMID 38651159, 2023). "Then, mice with intestinal specific AhR deficiency (AhRfl/fl Cre) were generated and were used in 2 murine models: AOM/DSS treatment as a model of carcinogen-induced colon cancer and a genetically induced model using ApcMin/+ mice." (PMID 37781044, 2023). "Some reports show that the AhR exhibits pro-oncogenic activity in colon cancer; however, most studies on colon cancer indicate that the AhR is a tumor suppressor and tumor growth is inhibited by AhR agonists." (PMID 38651159, 2023). "The inflammation-induced colon cancer mouse model was used for investigating the mechanisms of AhR-mediated effects on colonic stem cells and colon tumor formation." (PMID 38651159, 2023). "High-throughput RNA sequencing in colon cancer cell lines has identified a signature of AhR target genes regulated by exogenous ligands of AhR of the TCDD type and by endogenous ligand Kyn, a tryptophan metabolite." (PMID 37232717, 2023). "The effects of tissue-specific AhR loss in the intestine of the tumor-forming mice on colonic stem cells, organoid-initiating capacity, colon tumor formation and mechanisms of AhR-mediated effects were investigated." (PMID 38651159, 2023). "By contrast, there is an example of a different effect of Wnt/β-catenin signals on AhR signaling: HCT116 human colon cancer cells, where the genotoxicity of BaP has been investigated." (PMID 37232717, 2023). "In the present study, we employed AhR KO models of two colon carcinoma cell lines in order to better understand the impact of this transcription factor, which is frequently overexpressed in colon tumors, on their proliferative and metabolic behavior." (PMID 36077780, 2022). "In order to analyze the potential role of the AhR in control of colon carcinoma cell behavior, we employed the AhR KO clones derived from parental HT-29 and HCT116 cells lines by CRISPR/Cas9 technique." (PMID 36077780, 2022). "The Wnt/β-catenin signaling pathway is an important regulator of proliferation of colon cancer cells, and it has been proposed to be inhibited via the AhR-mediated degradation of β-catenin in colon epithelial cells." (PMID 36077780, 2022).